GSN (gelsolin)
Diseases named in the same sentence as GSN in open-access papers (continued):
Sharing a sentence is not in itself a finding about the gene and the disease.
tumor (continued). "The invasive front (arrow) showed stronger GSN immunoreactivity than the central tumor in seven patients (35%; 4 patients with recurrence and 3 patients without recurrence), whereas OAS2 immunoreactivity was not different between invasive front and central tumor regardless of recurrence." (PMID 30148861, 2018). "Gelsolin has a tumor suppressor activity in breast cancers, although the role of gelsolin in HCC remains unknown." (PMID 28993697, 2017). "To confirm the requirement of O2.- in tumor cell invasion, we asked if an increase in O2.- could phenocopy the effect of gelsolin in cells where the expression of gelsolin had been repressed by siRNA-mediated gene silencing." (PMID 27391159, 2016). "Notably, we have delineated a new role of gelsolin in creating a pro-oxidant milieu that favors tumor cell invasion." (PMID 27391159, 2016). "Since tumor cells may secrete different proteases during the course of dissemination, we investigated whether the gelsolin-mediated invasion may involve, besides uPA, members of the MMP family." (PMID 22927998, 2012). "It is likely that the role of gelsolin differs during the course of tumor progression, and in more advanced disease gelsolin may cooperate with other oncogenic factors to accelerate progression." (PMID 22927998, 2012). "Gelsolin was detectable in the cytoplasm as well as the nuclei of tumor cells." (PMID 22927998, 2012). "Increased expression of gelsolin may facilitate a subset of tumor cells with increased motility, thereby enhancing its capability and probability of invading adjacent tissues and metastasis to remote organ sites." (PMID 16882345, 2006). "In summary, higher expression in MCM2 and gelsolin was significantly associated with poorer prognosis in patients with NSCLC, which suggests that higher tumor proliferation and motility may be important in the prognosis of NSCLC." (PMID 16882345, 2006). "All these findings suggest that downregulation of gelsolin is involved in the development of various cancers as one of the early events in carcinogenesis, and that gelsolin may function as a tumour suppressor." (PMID 12592377, 2003). "We next studied in vitro whether gelsolin overexpression led to tumour regression because cell proliferation was restrained or because the apoptotic process was enhanced in PGs or both." (PMID 12592377, 2003). "Therefore, the authors concluded that increased gelsolin expression could indicate the conversion of a superficial tumor into an invasive tumor." (PMID 39061201, 2024). "In addition, GSN expression was correlated with various inflammatory cells and may influence the immunity of the tumor microenvironment." (PMID 37958747, 2023). "In addition, we have found a correlation between expression of gelsolin and tumor stage in LSCC." (PMID 34144901, 2022). "Consequently, tumor cells might upregulate gelsolin to increase movement capability, as achieving highly mobile behavior is considered a prerequisite for the spread of a tumor cell to adjacent tissues and distant metastasis." (PMID 34144901, 2022). "In addition, these data showed that GB-induced CMA in PCs also leads to the secretion of molecules that can promote pro-tumor immune responses, such as gelsolin, periostin, and osteopontin, supporting previous data showing the contribution of the PC secretome to GB immune evasion." (PMID 36012149, 2022). "Besides, it is reported that elevated GSN expression is associated with angiogenesis in an in vitro model of VEGF-A-induced angiogenesis, indicating that GSN may promote vascularization in tumour tissue." (PMID 32377190, 2020). "Moreover, GSN also supports the growth and metastasis of tumor cells." (PMID 32034162, 2020). "However, GSN has a dual function as tumor suppressor or promoter." (PMID 30148861, 2018). "Indeed, contradictory results might have been observed even in the same types of cancer, possibly because the role of gelsolin differs during the course of tumor progression." (PMID 30149613, 2018).
tumor (continued). "Disruption of the gelsolin-Cu/ZnSOD complex by small molecules would restore Cu/ZnSOD activity thereby reducing intracellular levels of O2.- which could have potential implications for the design of therapeutic strategies to combat tumor invasive capacity." (PMID 27391159, 2016). "Extending the similarities of the arthritic synovium with tumours, gelsolin was found to be one of the most strikingly down-regulated markers upon malignant transformation of fibroblasts by Ras, while overexpression of a gelsolin mutant was shown to suppress Ras-induced transformation." (PMID 16254600, 2005). "In EAC tissue, TRPA1 expression was localised to subpopulations of CAFs surrounding tumours, presumed to be CAF5, whereas GSN was more broadly expressed, localising to both intratumoral fibroblast and lymphocyte populations." (PMID 40640495, 2025). "In this study, we examined the prognostic significance of nuclear PD-L1 and its interactions with plasma gelsolin (pGSN) and CD8+ T cells within the tumor microenvironment." (PMID 40726982, 2025). "Conversely, GSN and PGR exhibited lower protein expression in tumor tissues relative to normal tissues, aligning with their favorable prognostic roles and reduced expression in the high-risk group." (PMID 41244925, 2025). "Within EAC tumours and patient-derived CAF cultures we observed down-regulation of GSN and conversely, GSN was upregulated in responders to NAT in the residual CAF subtypes (CAF1, 3 and 4)." (PMID 40640495, 2025). "In contrast, the reduced expression of GSN and PGR in tumor tissues supports their role as favorable prognostic markers, potentially through impaired cell adhesion and hormone response, respectively." (PMID 41244925, 2025). "GSN is a cytoskeletal protein that can promote epithelial-to-mesenchymal transition (EMT) signaling and subsequent tumor invasion." (PMID 37158852, 2023). "For example, C03_PI16 expressed several marker genes, such as COL14A1, CFD, GSN and PI16, similar to the major fibroblast subpopulations in normal tissue and early‐stage tumour in a previous study." (PMID 38115703, 2023). "Noteworthily, this study is the first to determine the roles of GSN and PRDX4 in the migration and invasion of CRC and tumor growth in nude mice xenograft models of cancer." (PMID 35804959, 2022). "The transfection of the DLD-1 cells with GSN shRNA and PRDX4 shRNA led to significantly decreased tumor weight in tumor tissues compared with that of the DLD-1 cells (Control shRNA) in mouse xenografts." (PMID 35804959, 2022). "Therefore, GSN is considered a promising biomarker in the early stage of tumor invasion and metastasis and might become an effective molecular target to identify and screen tumor metastasis through the lymphatic system." (PMID 36338135, 2022). "Gelsolin has also been found to be packaged into exosomes and secreted, termed plasma gelsolin (pGSN), with this form inhibiting CD8+-mediated tumor immune surveillance." (PMID 34948433, 2021). "Tumor ECs in early-stage tumors strongly expressed PLVAP, GSN, and TSC22D1, which are relevant to the development and cell-fate commitment of ECs15." (PMID 34764257, 2021). "In our study, GSN was overexpressed in NAT and slightly but significantly overexpressed in PTC tumor." (PMID 34238982, 2021). "In fact, high expression of gelsolin, CapG, Stathmin, CCT8 and Rho GTPases have all been described to promote tumor cell migration, invasion and formation of metastases in various tumor entities." (PMID 32545200, 2020). "We have established a four molecular pathway foundation (ANXA2/HMGA1/POU3F1; NFRSF13/GSN; TMOD3/RAI14/VWF; PLAT/PLAU) behind HO-1 regulation of the tumor cytoskeletal compartments." (PMID 32640729, 2020). "To further elucidate the role that GSN plays in HCC, we investigated GSN expression in HCC, its impact on patient survival, and its relationship with the tumour stage." (PMID 32377190, 2020).
tumor (continued). "Genes ASPH, HSPB1, SQSTM1, ANXA2, and GSN (Cluster A) and PURA and MX1 (Cluster B) were downregulated for both datasets in PCa tissue vs. normal gland or normal adjacent to tumor tissue." (PMID 32640729, 2020). "We provide evidence that increased gelsolin expression in HCT116 cells creates a pro-oxidant milieu and promotes tumor cell invasion." (PMID 27391159, 2016). "The integration from our omics-based research provides a four molecular pathway foundation (ANXA2/HMGA1/POU3F1; NFRSF13/GSN; TMOD3/RAI14/VWF; and PLAT/PLAU) behind HO-1 regulation of tumor cytoskeletal cell compartments." (PMID 28032857, 2016). "Among the commercially-available cell lines, the ascites-derived COLO201 and COLO205 and the primary tumor cell lines DLD-1 and LS513 expressed the highest levels of gelsolin." (PMID 22927998, 2012). "Our results were consistent with those of the meta-analysis such that GSN, SPTBN1, SFRP1 and MAF were down-regulated in most tumor samples with respect to their matched non-tumor samples whereas COX6C, RAD21, GSPT1, NME1 and PTTG1 were up-regulated." (PMID 19116033, 2008). "In several types of cancer including hepatocellular carcinoma, head and neck squamous cell carcinoma, stomach adenocarcinoma and ovarian cancer, overall patient survival appears to be favored by low levels of soluble gelsolin and higher levels of CLEC9A present in the tumor bed." (PMID 37907944, 2023). "Tumors can also modulate cDC1s’ cross-presentation capacity of tumor antigens—through gelsolin secretion in the TME of a melanoma mouse model—by inhibiting F-actin recognition by Clec9α, leading to a decreased proportion of tumor-infiltrating cytotoxic T-cells." (PMID 37190135, 2023). "In order to investigate and compare the co-expression of adhesion molecules (CDC42, TAGLN, and GSN) in cancerous and healthy samples, 100 co-expressed genes were retrieved from GEPIA2 using data from TCGA COAD tumor samples, TCGA adjacent normal tissue samples, and GTEx healthy colon samples." (PMID 37365287, 2023). "On the other hand, the Wnt/β-catenin signaling pathway also provides a mechanism for the action of GSN and PRDX4, which might broadly regulate the transcription of other genes and influence the processes relevant to the tumor’s microenvironment and metastasis." (PMID 35804959, 2022). "These unique features of GSN and PRDX4 upregulation in tumor cells may play an important role in the oxidative stress response—an anti-apoptotic function." (PMID 35804959, 2022). "The functional roles of GSN and PRDX4 in tumor growth, migration, and invasion of CRC remain unclear." (PMID 35804959, 2022). "The prognostic significance of gelsolin was shown to be independent of clinicopathological parameters (age, sex, tumor location, histological location, TNM stage, lymph node status, PNI, and LVI) of the patient (HR = 2.63, 95% CI 1.27–6.67, p = 0.025)." (PMID 34144901, 2022). "There was not a significant relationship between Gelsolin gene expression levels and tumor size or tumor histologic grades." (PMID 33391377, 2021). "Meanwhile, the expression of Gelsolin was significantly lower and the expression of Scinderin was significantly higher in tumor tissues compared to non-tumor tissues obtained from the same patients in this study." (PMID 32636728, 2020). "We found that GSN expression was higher in HCC tissues than in adjacent liver tissues, whereas GSN expression was higher in metastatic HCC tumour tissues than in nonmetastatic HCC tumour tissues." (PMID 32377190, 2020). "Our work revealed that GSN can promote EMT signalling and subsequent tumour invasion." (PMID 32377190, 2020). "IHC analysis of a separate set of tumor tissues from 20 patients (10 patients each with and without recurrence) detected cytoplasmic expression of GSN and OAS2." (PMID 30148861, 2018).
tumor (continued). "It revealed that all these five targets (GSN, ADAMTSL4, CALR, PPIA and TXN) can be secreted by the NPC 6-10B and 5-8F cells, which provided an important basis for our following studies to identify the serum tumor biomarkers of NPC." (PMID 28107202, 2017). "In some PCa tissues, in which gelsolin was not highly expressed, clear swarms of tumor-infiltrated lymphocytes (TIL) were detected around the tumor nests." (PMID 29100377, 2017). "Strikingly, when integrating the transcriptome under HO-1 modulation with the HO-1 interactome, a framework of four main molecular pathways arose as the foundation for the regulation of the tumor cell protrusive forces: ANXA2/HMGA1/POU3F1; NFRSF13/GSN; TMOD3/RAI14/VWF; PLAT/PLAU." (PMID 28032857, 2016). "There were no significantly difference of tumor size in MGC cell xenograft mouse model with over-expression or knockdown of gelsolin." (PMID 27419625, 2016). "To investigate whether downregulation of GSN could decrease the cytotoxicity of CD8+ T cells in vitro, we isolated primary CAFs and primary ccRCC tumour cells from tumour samples of HLA‐A2+ ccRCC patients, and we also isolated CD8+ T cells from PBMC of the same patient." (PMID 40375605, 2025). "We observed that GSN expression was positively correlated with the infiltration level of most immunity cells, like DC cells, macrophages, NK cells, Tem, TFH and other immune cells involved in anti-tumor immune effects, and CAF involved in tumor immune evasion or suppression." (PMID 37035750, 2023). "GSN was low expressed in most cancers, so we speculated that GSN is mainly involved in immune effects in the TME through anti-tumor immune invasion rather than immune escape or immunosuppression." (PMID 37035750, 2023). "FOX and GSN genes were highly expressed in the nonresponses of fibroblasts and endothelial cells, respectively, might serve as a potential target for relieving tumor immunosuppression." (PMID 37152010, 2023). "The secreted gelsolin component of the plasma actin-scavenging system impairs the ability of the receptor DNGR-1 to recognize dead cells and selectively dampens cross-presentation of tumor antigens by type 1 dendritic cells, acting as a barrier to anti-tumor immunity." (PMID 34081922, 2021). "Moreover, lymphocytes that had not yet entered tumor nests, were gelsolin-negative, indicating that lymphocytes might gain gelsolin during their infiltration of PCa nest." (PMID 29100377, 2017). "Surrounding tumour nests, we found distinct peritumoral stromal regions positive for POSTN/α-SMA (i.e., myoCAFs) that did not appear to express GSN, and sub-populations expressing TRPA1." (PMID 40640495, 2025).
cancer (112 papers, 2003 to 2025). A tumor composed of atypical neoplastic, often pleomorphic cells that invade other tissues. "To date, no major naturally occurring mutation, deletion, or rearrangement in the gelsolin gene has been identified that regulate its role in the context of cancer." (PMID 38216951, 2024). "GSN plays roles as both the effecter and inhibitor of apoptosis, which underlines its association in a wide variety of cancer types." (PMID 39149564, 2024). "We utilized the GSCA database to examine the association between GSN methylation patterns and GSN mRNA expression and their influence on the outcome of cancer patients." (PMID 37035750, 2023). "The authors proposed that gelsolin has the properties to be a pan-cancer diagnostic, predictive, and immune indicator." (PMID 37373424, 2023). "Our GSEA results showed that among cancer types with a favorable outcome associated with GSN expression, genes positively related to GSN expression were mainly enriched in the immune-associated reactome pathway." (PMID 37035750, 2023). "Subsequently, we utilized the GSCA database to study the association between GSN mutation and GSN mRNA expression and GSN mutation and outcome of cancer patients." (PMID 37035750, 2023). "We are the first to reveal the significance of GSN mutations in pan-cancer, but more research is required to identify the pathway." (PMID 37035750, 2023). "Among the cancer types whose expression was positively associated with prognosis, GSN was negatively correlated with immune function." (PMID 37035750, 2023). "There are conflicting reports regarding the expression of gelsolin and the association between gelsolin and prognosis in cancer." (PMID 36291171, 2022). "Gelsolin is associated with motility, apoptosis, and is indicative of cancer phenotype while it is considered to be an activator and an inhibitor of apoptosis in different cancers." (PMID 33391377, 2021). "The GSN gene encodes gelsolin, which is a calcium-regulated actin regulatory protein that involved in inflammation, cell movement, apoptosis, and cancer development." (PMID 33192475, 2020). "In non-small-cell lung cancer, variable level of gelsolin expression was associated with poor survival and this pattern was mostly observed with patients in stage II cancers." (PMID 33171868, 2020). "Consistently, gelsolin, as one of the best-known actin cytoskeleton-affecting agents, was found to be implicated in cancer development." (PMID 30149613, 2018). "These spanned the two forms of hsa-miR-133, previously linked to PD (hsa-miR-133a, predicted to bind the GTPase GSN and the cancer-linked FRG1B, and hsa-miR-133b, also predicted to bind FRG1B." (PMID 24651478, 2014). "Gelsolin is reported to be down-regulated in tumors including breast and lung carcinomas, suggesting that loss of gelsolin promotes oncogenesis." (PMID 22927998, 2012). "SEMG1, CLU and GSN have been reported to be associated with cancers." (PMID 38763993, 2024). "Similarly, our GSEA analysis showed that in cancer types where GSN expression was negatively associated with prognosis, GSN was positively correlated with immune function." (PMID 37035750, 2023). "Altered expression of GSN was associated with many different diseases including cancer." (PMID 37958747, 2023). "In many cancers, GSN expression was significantly linked to mDCs invasion." (PMID 37035750, 2023). "Gelsolin is an actin binding protein implicated in migration and invasion of cancer cells." (PMID 36059515, 2022). "GSN expression may also be associated with survival from malignant BC, and the frequency of GSN deficiency increases significantly with progression to invasive phenotypic cancer cells, according to clinical evidence." (PMID 35205837, 2022). "First, GSN is implicated in many relevant cellular processes, including cytoskeletal remodeling during heart development, pathological cardiac remodeling, and some forms of cancer." (PMID 34685680, 2021).